GIT1 (GIT ArfGAP 1)
Diseases named in the same sentence as GIT1 in open-access papers (continued):
Sharing a sentence is not in itself a finding about the gene and the disease.
tumor (continued). "GIT1 Expression Dataset consisting of 522 primary tumors, 3 metastatic tumors, and 22 tumor-adjacent normal samples." (PMID 29862012, 2017). "To explore this phenomenon further, we carried out a comparative analysis of GIT1 expression between the primary tumour site and matched synchronous lymph node metastasis." (PMID 29862012, 2017). "When we compared GIT1 expression in primary tumours with that of their counterpart lymph node metastases surprisingly we observed a significant decrease of GIT1 expression (p=0.0054)." (PMID 29862012, 2017). "Out of the 140 primary tumour specimens, we observed high expression of GIT1 in 47 cases (34%), moderate expression in 58 cases (42%) and no GIT1 expression in 35 cases (25%)." (PMID 29862012, 2017). "We observed both cytoplasmic and membrane expression of GIT1 in tumour cells of varying intensities, along with some perinuclear localisation and some weaker signal in stromal cells." (PMID 29862012, 2017). "In sum, we have demonstrated that GIT1 was overexpressed in NSCLC as compared to non-tumor lung tissues and was related to poor prognosis of NSCLC." (PMID 26462147, 2015). "It is also worth noting the significant correlation we found between GIT1 and tumor grade and progression." (PMID 26462147, 2015). "Together, our data suggest an important role of GIT1 signaling axis in the regulation of cell mobility and tumor metastasis in NSCLC." (PMID 26462147, 2015). "At 12 h treatment, gefitinib induced the expression of HDAC5, a growth inhibitory tumor suppressor and pro-apoptotic factor, in Hec50co cells, while regulators of cell migration and morphogenesis such as GIT1 and CALD1 were down-regulated by gefitinib." (PMID 20579378, 2010). "To determine whether the GIT1-Notch axis plays a role in tumour progression, we assessed the growth of genetically modified MDA-MB-231 and HCC1395 cells xenografted into immunodeficient nude mice." (PMID 35318302, 2022). "However, the function of GIT1 in tumour biology is complex, and involves multiple signalling pathways." (PMID 35318302, 2022). "The level of GIT1 had a marked effect on tumour xenograft formation by TNBC cells." (PMID 35318302, 2022). "GIT1 is involved in the regulation of tumor cell invasion and migration by modulating EMT." (PMID 33258389, 2021). "Moreover, our findings indicated that GIT1 enhances tumor progression by modulating EMT and is a predictor for poor prognosis in HCC." (PMID 33258389, 2021). "In this study, GIT1 expression in HCC tissues exceeded that in adjacent non-tumor tissues." (PMID 33258389, 2021). "As recent studies have revealed that GIT1 is related to tumour migration and invasion, we analysed GIT1 protein expression using Western blot analysis and found an approximate 60% reduction and 1.4‐fold increase following transfection with pcDNA‐lincFOXF1 and si‐lincFOXF1 respectively." (PMID 32945076, 2020). "In order to ascertain the association of tumoural GIT1 expression with clinicopathological characteristics, we scored the expression according to intensity and % positive tumour cells in each case (based on two cores) as negative, moderate and high." (PMID 29862012, 2017). "Relationship between GIT1 expression in primary tumour and lymph node metastasis." (PMID 29862012, 2017). "GIT1 expression in tumour cells was scored and statistical correlation analyses were carried out." (PMID 29862012, 2017). "However, since the primary tumor growth was also affected by GIT1 manipulations, especially GIT1 depletion, our data still cannot rule out the effects of metastasis from difference of primary tumor size." (PMID 26462147, 2015). "We next examined the in vivo effects of GIT1 expression on tumor growth and metastasis." (PMID 26462147, 2015). "In xenografted mice, stable expression of DNMM1 alone prevented tumour development, and expression of DNMM1 together with GIT1 shRNA dramatically attenuated the tumour growth-promoting effect of GIT1 knockdown." (PMID 35318302, 2022).
tumor (continued). "In addition, both MAT2B splicing variants are able to interact with G Protein Coupled Receptor Kinase Interacting ArfGAP 1 (GIT1) recruiting and activating mitogen-activated protein kinase kinase (MEK) and ERK promoting growth and tumor formation, and also activating Ras/Raf." (PMID 39941901, 2025). "Therefore, we believe that GIT1 may be a carcinogen of HNSCC and promote the occurrence and development of tumour, or may be a potential target for HNSCC therapy by inhibiting GIT1." (PMID 36600313, 2023). "We found 64 cases (63%) with concordant GIT1 expression, either both positive for GIT1 expression (scores >1, n=45 (44%), or both negative for GIT1 expression (scores<1, n=19 (19%), and 38 cases (37%) with discordant GIT1 expression between the primary tumour and the lymph node." (PMID 29862012, 2017). "In a comparative experiment, in which tumor metastases were rarely seem in the right lung of the mice carrying the primary tumors generated from control CL1–0 cells, enhanced lung metastasis nodules were frequently observed in the right lung of GIT1 overexpression group (P = 0.002)." (PMID 26462147, 2015).
neurodevelopmental disorder (1 paper, 2016). A behavioral and cognitive disorder with onset during the developmental period that involves impaired or aberrant development of intellectual, motor, or social functions. "We identified genes containing CNVs previously considered to be VOUS to be new candidate genes for neurodevelopmental disorders (GIT1, MVB12B and PPP1R9A) demonstrating the utility of this strategy to index the clinical effects of CNVs." (PMID 27363808, 2016).
neurological disorders (1 paper, 2025). "These modules suggested the involvement of multiple novel genes for the first time including CFL1, GIT1, CDK5a, and CRMP2 and their signaling pathways which were related to the nervous system and neurological disorders including Eph‐ephrin signaling and semaphorin interactions." (PMID 41255384, 2025).
GIT1 also shares sentences with these, for which no sentence is quoted: non-small cell lung carcinoma (4 papers); cognitive defects (2); adenocarcinoma (1); asthma (1); bipolar disorder (1); clear cell renal cell carcinoma (1); colorectal cancer (1); depression (1); developmental delay (1); endothelial dysfunction (1); glioma (1); hepatitis C (1); invasive carcinoma (1); invasive lobular carcinoma (1); large cell carcinoma (1); liver cancer (1); memory impairment (1); metastatic tumors (1); ovarian carcinoma (1); pancreatic cancer (1); Seckel syndrome (1); spinal cord ischemia (1); squamous cell carcinoma (1); X-linked intellectual disability (1).